RNU6-805P (RNA, U6 small nuclear 805, pseudogene)
Gene: Small nuclear RNA gene on chromosome 10 (72,391,964 to 72,392,069, forward strand). Ensembl gene ENSG00000202513.
Homologues: Orthologues: chimpanzee U6 (100% identical), macaque U6 (93% identical), dog U6 (86% identical), rat U6 (82% identical), rabbit U6 (81% identical). Paralogues in human: RNU6-12P (90% identical), RNU6-13P (90% identical), RNU6-32P (90% identical), RNU6-36P (90% identical), RNU6-7 (90% identical), RNU6-8 (90% identical), RNU6-1 (89% identical), RNU6-140P (89% identical), RNU6-17P (89% identical), RNU6-18P (89% identical), RNU6-19P (89% identical), RNU6-2 (89% identical), and 1285 more.